PGF (placental growth factor)
Diseases named in the same sentence as PGF in open-access papers (continued):
Sharing a sentence is not in itself a finding about the gene and the disease.
atherosclerosis (19 papers, 2010 to 2025). A disease characterized by the build-up of fatty material and calcium deposition in the arterial wall resulting in partial or complete occlusion of the arterial lumen. "On the other hand, it has been also reported that the placental growth factor (PlGF) plays an important role in atherosclerosis by stimulating the angiogenesis and atherogenic migration of monocytes/macrophages into the arterial wall." (PMID 28883908, 2017). "Placental growth factor (PlGF) is a member of the vascular endothelial growth factor (VEGF) family cytokines and is associated with inflammatory progress of atherosclerosis." (PMID 20500895, 2010). "Aldosterone-activated MR regulates the expression of target genes, such as placental growth factor (PIGF), promoting the proliferation of VSMCs and the aggregation of monocytes and contributing to the development of atherosclerosis." (PMID 40244230, 2025). "FGF23, HO1, PGF, and CD40L were related to cardiovascular damage, such as atherosclerosis and infarction." (PMID 38958674, 2024). "This is the case of the angiogenic placental growth factor (PlGF), which activates VEGFR-1, which is subsequently involved in T cell activation and infiltration in target organs including the myocardium and the arterial wall, contributing to HMOD, renal failure, atherosclerosis and heart failure." (PMID 36430599, 2022). "Aldosterone promotes inflammatory plaque formation via placental growth factor (PlGF) which binds to VEGF type 1 receptors on endothelial and inflammatory cells, and further promotes vascular smooth cell proliferation and monocyte chemotaxis, which are fundamental processes of atherosclerosis." (PMID 35677685, 2022).
colorectal cancer (19 papers, 2010 to 2025). A primary or metastatic malignant neoplasm that affects the colon or rectum. "On the contrary, in colorectal cancer, METTL3-mediated m6A modification enhances the binding of circALG1 to miR-342-5p, thereby upregulating placental growth factor (PGF) expression, which accelerates cancer cell metastasis." (PMID 38125749, 2023). "Additional evidence for the efficacy of anti-angiogenic therapy in colorectal cancer comes from a study of aflibercept, a novel fusion protein that binds to three VEGF family ligands: VEGF-A, VEGF-B and placental growth factor (PLGF)." (PMID 24482243, 2014).
diabetic retinopathy (19 papers, 2011 to 2025). "Placental growth factor has been implicated in the pathogenesis of diabetic retinopathy and DME." (PMID 38916818, 2024). "Vascular endothelial growth factor (VEGF) and placental growth factor (PlGF) plays a crucial role in breakdown of the blood-retinal barrier due to hyperpermeability in diabetic retinopathy (DR)." (PMID 31653890, 2019). "There are controversies regarding the pro-angiogenic activity of placental growth factor (PGF) in diabetic retinopathy (DR)." (PMID 21408222, 2011).
chronic kidney disease (17 papers, 2013 to 2025). Impairment of the renal function secondary to chronic kidney damage persisting for three or more months. "Soluble Flt-1 (sFlt-1), an endogenous antagonist of the proatherogenic cytokine placental growth factor, is decreased in chronic kidney disease (CKD), leading to atherosclerotic progression." (PMID 31666542, 2019). "The inclusion of controversial factors such as chronic kidney disease, serum uric acid levels, alanine aminotransferase levels, placental growth factor, vascular endothelial growth factor levels, hemoglobin concentration, and platelet count provides convincing evidence." (PMID 39286274, 2024).
gestational diabetes (17 papers, 2010 to 2025). Carbohydrate intolerance first diagnosed during pregnancy. "Is placental growth factor (PlGF) testing at the time of gestational diabetes screening among unselected, singleton pregnancies associated with higher risk for early preterm birth (ie, <34 weeks)?" (PMID 39541121, 2024). "Background and objectives: To assess whether placental growth factor (PlGF) levels may have a predictive value for the onset of gestational diabetes mellitus (GDM) and thyroid dysfunction during pregnancy." (PMID 35208556, 2022).
glioma (17 papers, 2015 to 2026). A benign or malignant brain and spinal cord tumor that arises from glial cells (astrocytes, oligodendrocytes, ependymal cells). "It has been reported that glioma cell-derived placental growth factor (PlGF) is also involved in the generation of regulatory B cells." (PMID 39744696, 2025). "Glioma cells secrete placental growth factor (PlGF) in exosomal form, which in contact with naïve B cells can induce their differentiation to Bregs." (PMID 36467419, 2022). "TGF-β induces VEGF and placental growth factor (PlGF) mRNA and protein expression in glioma cells inducing pro-angiogenic effects." (PMID 32152825, 2020). "For instance, glioma cells release Placental Growth Factor (PlGF) to induce a Breg phenotype." (PMID 41614936, 2026). "Secreted factors such as leukotriene B4 (breast cancer), glioma cell-derived placental growth factor (glioma), TNF-α (tumor cells), and IL-21 (T cells), as well as cell contact-dependent mechanisms (CD40-CD40L and PD-1-PD-L1 axis,), promote cell differentiation Bregs in the TME." (PMID 37568713, 2023). "Plasma GFAP may, together with plasma placental growth factor (PlGF), differentiate between radiologically suspected high-grade glioma and brain metastases." (PMID 25720744, 2015).
lung carcinoma (14 papers, 2005 to 2025). "Despite the high gene expression levels of VEGFA, PGF, FLT1, KDR, MMP-2, TIMP-1, and TIMP-2, only KDR and TIMP-1 were high at the protein level in the lung cancer resections." (PMID 22593690, 2012). "We sought to develop placental growth factor as a predictive pharmacodynamic biomarker for motesanib efficacy as first-line therapy in patients with advanced nonsquamous non–small-cell lung cancer." (PMID 25314641, 2014). "Insulin-like growth factor 1 (IGF1) was found to initiate self-renewal of lung cancer stem cells in dormant lung tumors via the activation of a PI3K/Akt/β-catenin pathway and production of the angiogenic factors chemokine (C-X-C motif) ligand 1 (CXCL1) and placental growth factor (PlGF)." (PMID 30603045, 2018).
hepatocellular carcinoma (13 papers, 2012 to 2024). A malignant tumor that arises from hepatocytes. "Nonetheless, an increase of the mRNA levels of PGF was already associated to IRE1 activation in the hepatocellular carcinoma HepG2 cell line, which matches with our results for both cannabinoids." (PMID 38748041, 2024). "We obtained a prognostic signature including eight hypoxia genes (ENO2, KDELR3, PFKP, SLC2A1, PGF, PPFIA4, SAP30, and TKTL1) and further established a hypoxia-related prognostic ceRNA network including 17 lncRNAs, six miRNAs, and seven mRNAs for hepatocellular carcinoma." (PMID 36362375, 2022). "Among the eight mRNAs in the model, the up-expressions of TKTL1, KDELR3, PFKP, SLC2A1, and PGF in hepatocellular carcinoma were confirmed in previous experimental studies, while the over-expression of SAP30 in HCC was reported in an earlier computational study." (PMID 36362375, 2022).
myocardial infarction (13 papers, 2011 to 2025). Gross necrosis of the myocardium, as a result of interruption of the blood supply to the area, as in coronary thrombosis. "Placental growth factor (PlGF) emerges as a stimulator of angiogenesis, enhancing cardiac function post-acute myocardial infarction." (PMID 38738046, 2024). "Hypoxia increases PGF expression in human myocardium, and pathological cardiac conditions such as ischemic cardiomyopathy or acute myocardial infarction result in elevated plasma levels of PGF." (PMID 33178051, 2020). "Placental growth factor (PlGF) induces angiogenesis and promotes tissue repair, and plasma PlGF levels change markedly during acute myocardial infarction (AMI)." (PMID 26930634, 2016).
glioblastoma (12 papers, 2015 to 2025). The most malignant astrocytic tumor (WHO grade IV). "The anti-angiogenic medication Zaltrap/Aflibercept works by binding to vascular endothelial growth factor (VEGF) and placental growth factor (PLGF), which inhibits angiogenesis in patients with recurring glioblastoma, resulting in anti-tumor effects." (PMID 41041337, 2025).
Stroke (12 papers, 2013 to 2025). Sudden impairment of blood flow to a part of the brain due to occlusion or rupture of an artery to the brain. "In addition, mesenchyme homeobox 1 (Meox1), placental growth factor (pgf) and insulin-like growth factor binding protein 4 and 5 (Igfpb4 and 5) were among the genes associated with angiogenesis and upregulated following stroke." (PMID 32848875, 2020). "Our meta-analysis identified PGF as a risk gene for both MDD and stroke, and fine-mapping of TWAS signals further asserted that PGF is a possible causal gene for stroke." (PMID 34859065, 2021). "Cross-trait meta-analyses and fine-mapping of transcriptome-wide association signals identified novel risk genes for MDD and stroke, including RPL31P12, BORSC7, PNPT11, and PGF." (PMID 34859065, 2021). "Mesenchymal cells engineered to produce VEGF, BDNF, and placental growth factor were used for stroke treatment in a rat model." (PMID 29497380, 2018).
coronary artery disease (11 papers, 2011 to 2024). "The most studied factors as pertains to coronary disease are vascular endothelial growth factor (VEGF), placental growth factor (PlGF) and hepatocyte growth factor (HGF)." (PMID 22708908, 2012).
Miscarriage (11 papers, 2011 to 2025). A pregnancy that ends at a stage in which the fetus is incapable of surviving on its own, defined as the spontaneous loss of a fetus before the 22th week of pregnancy. "To investigate the possible role of DSC-derived PlGF in the maintenance of early pregnancy, we firstly analyzed the expression of PGF in DSCs from normal pregnancy and spontaneous abortion during early pregnancy." (PMID 37033974, 2023). "The increase in activating isoforms did not correlate with higher expression of TNF-α, IFN-γ, IL-10, and placental growth factor mRNAs in the placental tissue of those women who experienced sporadic miscarriage, as compared to those that had undergone elective abortions." (PMID 28424697, 2017).
pancreatic cancer (11 papers, 2011 to 2025). "However, an increased level of circulating PGF is associated with poor survival in patients with pancreatic cancer, and PGF expression in tumor tissue has been linked to CC tumor growth in tumor models." (PMID 36831406, 2023). "Additionally, miR-454 has been found to suppress the secretion of VEGF in pancreatic cancer, and the expression of placental growth factor in human microvascular endothelial cells." (PMID 32927780, 2020). "However, the association between PGF expression in pancreatic cancer tumors and prognosis has never been reported." (PMID 33291601, 2020). "Most pancreatic cancers display overexpression of key mediators of tumor angiogenesis, including the vascular endothelial growth factor (VEGF), tumor necrosis factor -α (TNF-α) and placental growth factor (PlGF)." (PMID 29069789, 2017).
emphysema (10 papers, 2008 to 2025). "Mechanistically, MMP-12 enhances placental growth factor (PGF) expression and upregulates its downstream signaling molecules, resulting in bronchial epithelial cell apoptosis and emphysema development." (PMID 39781522, 2025). "Placental Growth Factor (PLGF) is involved in emphysema pathogenesis through apoptosis regulation." (PMID 41226620, 2025). "Furthermore, this elastase induces autophagy through the upregulation of placental growth factor (PGF) which in turn promotes lung epithelial cell apoptosis and pulmonary emphysema." (PMID 28642633, 2017).
gastric cancer (10 papers, 2013 to 2025). A primary or metastatic malignant neoplasm involving the stomach. "Placental growth factor levels are high in gastric cancer tissue and are also associated with serosal invasion, lymph node metastasis, cancer stage, and survival rates." (PMID 34049591, 2021). "High expression of the PGF gene in gastric cancer was associated with an increased risk of lymph node metastasis and serosal invasion, and shorter survival." (PMID 32370309, 2020). "In the gastric cancer dataset, three genes—FOXS1, PGF, and CLDN1 —were commonly identified by both explainability methods and the manuscript, further validating their relevance." (PMID 40565055, 2025).
ovarian carcinoma (10 papers, 2012 to 2023). A malignant neoplasm originating from the surface ovarian epithelium. "Five feature genes were the up-regulation of placental growth factor (PGF), and PGF was reported to associate with unfavorable prognosis of ovarian cancer." (PMID 36905391, 2023). "In ovary carcinoma cells exposed to placental growth factor (PlGF), Orai1/STIM1 expression is enhanced, contributing to the upregulation of HIF-1α." (PMID 37833987, 2023). "In this study, other plasma biomarkers including IFNγ, IL-6, IL-8, IL-10, TNFα, placental growth factor (PlGF) were co-assessed with HSP90B1 and adjusted for the well-known cancer antigen CA-125 that is widely expressed in most ovarian cancers." (PMID 31540420, 2019). "Similarly, placental growth factor (PLGF) suppresses miR-543 and miR-543 which inhibits MMP7 translation, therefore high levels of PLGF as seen in ovarian cancer specimens increase MMP7 levels and thus the cancer’s invasion ability." (PMID 27231010, 2016).
heart failure (9 papers, 2012 to 2023). Inability of the heart to pump blood at an adequate rate to meet tissue metabolic requirements. "In contrast to wild-type mice, PGF KO mice do not form additional capillaries in response to aortic banding and rapidly develop heart failure, whereas mice overexpressing PGF show an increased angiogenic response." (PMID 29695980, 2018).
metastatic colorectal cancer (9 papers, 2012 to 2025). "In metastatic colorectal cancer patients, bevacizumab treatment was associated with increased plasma levels of placental growth factor (PlGF), FGF, and PDGF prior to and along disease progression." (PMID 38148844, 2023). "High serum levels of VEGFA and placental growth factor PlGF may be the basis of bevacizumab resistance in patients with metastatic colorectal cancer." (PMID 38687357, 2024). "PGF was reported to be associated with an angiogenesis pathway different from VEGF, and PGF blockade combined with the 5-FU + Folinic acid + Irinotecan (FOLFIRI) regimen improved the survival of patients with metastatic colorectal cancer who had resistance to chemotherapy." (PMID 32370309, 2020).
rheumatoid arthritis (9 papers, 2016 to 2025). A chronic, systemic autoimmune disorder characterized by inflammation in the synovial membranes and articular surfaces. "Recent work has demonstrated that placental growth factor, whose levels are increased in rheumatoid arthritis joints, could recruit bone marrow MSCs to the synovium." (PMID 27412524, 2016).
type 2 diabetes (9 papers, 2017 to 2026). "For example, the rs2268616 variant in the placental growth factor (PGF) gene has a stronger effect in men and people with type 2 diabetes." (PMID 41157147, 2025). "Within CKB, TFPI, PGF, F2R, and ASGR1 were each significantly associated with all 4 CVD risk factors (smoking, SBP, adiposity, and type 2 diabetes)." (PMID 37940228, 2023). "Moreover, FURIN, ASGR1, SORT1, TFPI, PGF, F2R, and EFNA1 were also associated with SBP, adiposity, and type 2 diabetes." (PMID 37940228, 2023).
age-related macular degeneration (8 papers, 2013 to 2025). Age-related loss of vision in the central portion of the retina (macula), secondary to retinal degeneration. "Several proangiogenic factors such as the vascular endothelial growth factor (VEGF) family and placental growth factor (PlGF) usually play a major role in the progression of cancer and age-related macular degeneration." (PMID 32560565, 2020).
Hyperglycemia (8 papers, 2019 to 2024). An increased concentration of glucose in the blood. "In GDM conditions, hyperglycemia, oxidative stress, and the increase in the release of placental-derived extracellular vesicles (PdEVs) and placental hormones, like placental growth factor (PlGF) and placental lactogen (hPL), contribute to periodontal inflammation." (PMID 34769262, 2021). "Other data show that as hyperglycemia increases, various cytokines (including IL-6) are augmented and a number of growth factors including vascular endothelial growth factor (VEGF) and placental growth factor (PlGF) are inhibited." (PMID 31647034, 2019).
acute coronary syndrome (7 papers, 2015 to 2023). Signs and symptoms related to acute ischemia of the myocardium secondary to coronary artery disease. "This study aimed to investigate the differences in level of several biomarkers, i.e. C-reactive protein, myeloperoxidase, soluble CD40 ligand and placental growth factor, between acute coronary syndrome and chronic stable angina patients." (PMID 26576922, 2015). "The concentration of these C-reactive protein, myeloperoxidase, soluble CD40 ligand and placental growth factor were significantly increased in acute coronary syndrome patients." (PMID 26576922, 2015).
cardiac hypertrophy (7 papers, 2014 to 2022). "Notably, overexpression of proangiogenic factors including the peptide regulator of angiogenesis (PR39) and Placental Growth Factor (PGF) in the heart were shown to induce cardiac hypertrophy." (PMID 35874523, 2022).
Cognitive impairment (7 papers, 2021 to 2025). Abnormal cognition is characterized by deficits in thinking, reasoning, or remembering. "At the same time, a higher expression of VEGFB, FLT4, FLT1, and PGF in the prefrontal cortex was related to the stronger cognitive impairments in patients indicating impaired neural network function." (PMID 33672819, 2021).
colon carcinoma (7 papers, 2012 to 2025). "In our study, we similarly observed significantly reduced expression of ANGPT2 in both right- and left-sided colon cancers, with FLT1 and PGF showing even lower expression in left-sided colon cancer." (PMID 41441010, 2025). "FLT1, a member of the VEGF receptor (VEGFR) family, along with ANGPT2 and PGF, plays a role in vascular development and contributes to colon cancer progression." (PMID 41441010, 2025). "mRNA levels of members of the Vascular Endothelial Growth Factor family (VEGF-A, -B, -C, -D, Placental Growth Factor/PlGF) have been investigated as tissue-based markers of colon cancer." (PMID 23148666, 2012). "Stimulation of colon cancer cells with VEGF-A and placental growth factor (PlGF) activated VEGF receptor-1 (VEGFR-1) and increased proliferation activity in an autocrine EGF/EGF receptor (EGF-R)-dependent manner." (PMID 31717527, 2019). "Fewer studies addressed the mRNA expression levels in colon cancer of the other VEGF family members: VEGF-B, VEGF-C, VEGF-D and Placental Growth Factor (PlGF)." (PMID 23148666, 2012).
liver disease (7 papers, 2010 to 2025). "Vascular endothelial growth factor (VEGF), placental growth factor (PlGF), and platelet derived growth factor (PDGF) are the leading secreted factors driving pathological angiogenesis in liver disease." (PMID 31921146, 2019).
macular edema (7 papers, 2015 to 2023). "Aflibercept, via binding vascular endothelial growth factor (VEGF) and placental growth factor (PlGF), effectively decreased macular edema by deactivating microglia and improving the drainage function of retinal Müller glia and retinal pigment epithelium." (PMID 35002773, 2021). "Though the pathogenesis is different, they both may cause retinal ischemia which gives rise to up-regulation of some cytokines such as vascular endothelial growth factor (VEGF), placental growth factor (PlGF), etc., and further lead to macular edema (ME)." (PMID 35355596, 2022).